AKR1B1 (aldo-keto reductase family 1 member B)
Description:
Catalyzes the NADPH-dependent reduction of a wide variety of carbonyl-containing compounds to their corresponding alcohols. Displays enzymatic activity towards endogenous metabolites such as aromatic and aliphatic aldehydes, ketones, monosaccharides, bile acids and xenobiotics substrates. It catalyzes the reduction of glucose to sorbitol, the first step of the polyol pathway, an alternative route of glucose metabolism that converts glucose to fructose. This pathway becomes highly active under elevated glucose levels, such as during hyperglycemia. Reduces steroids and their derivatives and prostaglandins. Displays low enzymatic activity toward all-trans-retinal, 9-cis-retinal, and 13-cis-retinal. Catalyzes the reduction of diverse phospholipid aldehydes such as 1-palmitoyl-2- (5-oxovaleroyl)-sn -glycero-3-phosphoethanolamin (POVPC) and related phospholipid aldehydes that are generated from the oxydation of phosphotidylcholine and phosphatdyleethanolamides. Plays a role in detoxifying dietary and lipid-derived unsaturated carbonyls, such as crotonaldehyde, 4-hydroxynonenal, trans-2-hexenal, trans-2,4-hexadienal and their glutathione-conjugates carbonyls (GS-carbonyls).
Synonyms: AR; ALDR1; ALR2; ADR
Tractability: Small molecule: an approved drug acts on it; a structure with a bound ligand is known; a high-quality ligand is known; it has a high-quality binding pocket; it belongs to a druggable protein family. PROTAC: ubiquitination databases record sites on it; its protein half-life has been measured; a small molecule that binds it is known.
Target class: Enzyme; Oxidoreductase
Gene: Protein-coding gene on chromosome 7 (134,442,349 to 134,459,284, reverse strand). Ensembl gene ENSG00000085662.
Subcellular location: Cytoplasm
Subcellular location (Human Protein Atlas): Cytosol; Nucleoplasm
Pathways (Reactome):
Metabolism: Fructose biosynthesis; Galactose catabolism; Pregnenolone biosynthesis
Gene Ontology:
Molecular function: aldose reductase (NADPH) activity; all-trans-retinol dehydrogenase (NADP+) activity; allyl-alcohol dehydrogenase activity; glyceraldehyde oxidoreductase activity; glycerol dehydrogenase (NADP+) activity; prostaglandin H2 endoperoxidase reductase activity; protein binding; retinal dehydrogenase (NAD+) activity; electron transfer activity; alcohol dehydrogenase (NADP+) activity; aryl-alcohol dehydrogenase (NADP+) activity; D-xylose reductase (NADPH) activity; L-arabinose reductase (NADPH) activity; L-glucuronate reductase activity; oxidoreductase activity; oxidoreductase activity, acting on the CH-OH group of donors, NAD or NADP as acceptor
Biological process: cellular hyperosmotic salinity response; daunorubicin metabolic process; doxorubicin metabolic process; retinoid metabolic process; sorbitol metabolic process; C21-steroid hormone biosynthetic process; carbohydrate metabolic process; fructose biosynthetic process; prostaglandin metabolic process; retinol metabolic process
Cellular component: cytosol; extracellular exosome; mitochondrion; nucleoplasm; extracellular region; cytoplasm
Genetic constraint (gnomAD): Loss-of-function variants: 23 observed, 43.47 expected, observed/expected ratio (o/e) 0.53, 90% interval 0.38 to 0.75. The upper end of that interval is the gene's LOEUF score, 0.75, which puts it in group 3 of 6, group 1 being the genes least tolerant of losing a copy. Missense variants: 357 observed, 410.25 expected, observed/expected ratio (o/e) 0.87, 90% interval 0.8 to 0.95. Synonymous variants: 157 observed, 157.47 expected, observed/expected ratio (o/e) 1, 90% interval 0.88 to 1.14.
Homologues: Orthologues: chimpanzee AKR1B1 (99% identical), macaque AKR1B1 (93% identical), dog AKR1B1 (90% identical), mouse Akr1b1 (85% identical), rat Akr1b1 (85% identical), guinea pig AKR1B1 (85% identical), pig AKR1B1 (84% identical), rat Akr1b1-ps2 (83% identical), rabbit AKR1B1 (79% identical), zebrafish akr1b1.2 (74% identical), zebrafish akr1b1.1 (72% identical), tropical clawed frog akr1b1 (72% identical), and 6 more. Paralogues in human: AKR1B10 (71% identical), AKR1B15 (65% identical), AKR1E2 (57% identical), AKR1A1 (51% identical), AKR1D1 (51% identical), AKR1C8 (51% identical), AKR1C2 (49% identical), AKR1C1 (49% identical), AKR1C4 (49% identical), AKR1C3 (48% identical), KCNAB2 (26% identical), KCNAB1 (26% identical), and 4 more.
Diseases named in the same sentence as AKR1B1 in open-access papers:
AKR1B1 is named in the same sentence as 162 diseases in open-access papers, as found by Europe PMC text mining. Sharing a sentence is not in itself a finding about the gene and the disease. The quoted sentences say what the papers report.
diabetes (188 papers, 2008 to 2026). "Aldose reductase (AKR1B1), the first rate-limiting enzyme involved in the polyol pathway, is linked to the pathogenesis of diabetes-related issues like cataracts, neuropathy, retinopathy and nephropathy." (PMID 38188141, 2024). "The gene with the highest correlation was AKR1B1, which has been associated with multiple complications of diabetes and plays a role in ROS production and promoting EMT." (PMID 38515837, 2024). "Considering that we used lens crystallin gene promoters in the transgene construct, we observed the expected strong expression of AKR1B1 in the lens and an associated elevated risk for diabetes-dependent cataract formation." (PMID 34357344, 2021). "The aldo-keto reductase AKR1B1 is associated with diabetes mellitus and is broadly overexpressed in human cancers; AKR1B1 overexpression is related to shortened patient survival in acute myelogenous leukemia and multiple myelomas." (PMID 32667929, 2020). "AKR1B1 (aldose reductase) is implicated in the complications that arise due to diabetes, since it converts high blood glucose to the hyperosmotic sugar sorbitol." (PMID 23162467, 2012). "Given the significant association between diabetes and increased cancer risk, AKR1B1 due to its involvement in the polyol pathway and oncogenic signaling could presumably emerge as a vital link in the context of coincident disease." (PMID 39055885, 2024). "Moreover, we identified some novel targets, 5-hydroxytryptamine 2A receptor (5-HT2A) and aldose reductase (AKR1B1), which are associated with diabetes." (PMID 31379563, 2019). "AKR1B1 is a cytosolic enzyme traditionally studied in the context of diabetes and metabolic disease due to its role in the polyol pathway, where it catalyzes the reduction of glucose to sorbitol." (PMID 41154825, 2025). "If needed, AKR1B1 inhibitors can be coadministered with conventional anticancer drugs in cancer patients with diabetes." (PMID 38200154, 2024). "Theoretically, it is plausible to test a combination therapy using AKR1B1 and KHK inhibitors to lower the risk of cancer metastasis in patients with diabetes." (PMID 38200154, 2024). "Studies of AKR1B1, an AKR family member, have focused more on diabetes, primarily its association with disease development and complications." (PMID 37751590, 2023). "Inhibition of AKR1B1 has also been evaluated in diabetes management with inhibition of AKR1B1 being shown to prevent advanced glycation end-product accumulation and atherosclerotic lesion formation." (PMID 36195845, 2022). "This in silico study revealed that the six known compounds have good inhibitory action to T2DM targets, namely, RBP4 and AKR1B1, which contribute in improving insulin sensitivity and prevent diabetes complication, respectively." (PMID 35807241, 2022). "We identified the significant T2DM targets of Asian propolis, namely retinol-binding protein-4 (RBP4) and aldose reductase (AKR1B1) that have important roles in insulin sensitivity and diabetes complication, respectively." (PMID 35807241, 2022). "Next, we treated H2009 cells with 100 μM epalrestat, a specific inhibitor of AKR1B1 that has been approved for the treatment of diabetes complications." (PMID 35962452, 2022). "The inflammatory disorder animal model like cardiovascular disease (CVD), diabetes, metastasis, uveitis, cancer and asthma, inhibiting AKR1B1 evidently promotes disease occurrence." (PMID 34112138, 2021). "Since AKR1B1 was shown to promote diabetic complications and play important role in oxidative stress during diabetes, AKR1B1 inhibition was able to attenuate alcoholic liver disease by AMPK activation and oxidative stress modulation." (PMID 34356319, 2021). "Mark Petrash (University of Colorado, USA) introduced an interesting concept where clues from Ayurveda led to a potential diabetes therapy directed at aldose reductase AKR1B1." (PMID 23199258, 2012).
diabetes (continued). "Due to its involvement in the development of diabetic complications, AKR1B1 is an attractive drug target in the clinical management of secondary complications of diabetes including cataract and retinopathy." (PMID 22485126, 2012). "Allelic and genotypic constitution of 10 polymorphisms (SNPs) from five genes namely- ADPRT1, AKR1B1, RAGE, GFPT2 and PAI-1 with diabetic CRI was investigated." (PMID 20353610, 2010). "These mice developed cataracts following diabetes induction, demonstrating an essential role for AKR1B1 in mediating high glucose-dependent cataract formation." (PMID 20628518, 2010). "AKR1B1 has emerged as a key regulator of the EMT, a process that underlies the progression and complications of a wide range of pathologies, including fibrosis, diabetes, and cancer." (PMID 41154825, 2025). "Contributing factors [including diabetes-induced overexpression of reactive oxygen species (ROS); secretion of inflammatory cytokines; increased aldose reductase (AKR1B1) substrate conversion; and activation of protein kinase C β, δ, and θ] accelerate the occurrence of MI." (PMID 33718461, 2021). "Chronic hyperglycemia in patients with diabetes mellitus (DM) leads to increased AKR1B1 affinity for glucose and, consequently, sorbitol accumulation." (PMID 35029856, 2022). "However, at high glucose concentration, specifically in diabetics, the combining capacity of aldose reductase (AKR1B1) to glucose is motivated and about one-third of the total glucose is metabolised through the polyol pathway in tissues such as lens, kidney, retina, and peripheral nerves." (PMID 31347930, 2019). "In our earlier study, spongiacidin PIAs were determined to have inhibitory activities against aldose reductase (AKR1B1), a target of complications of diabetes." (PMID 39452885, 2024). "Aldose Reductase (AKR1B1) and Protein Tyrosine Phosphatase 1B (PTP1B) represent two insulin-resistance-related targets involved in the development of type 2 diabetes mellitus (T2DM) and its chronic complications." (PMID 36839851, 2023). "AKR1B1 is an aldo-keto reductase (AKR), which plays a role in cellular defense and signaling, and is involved in complications of diabetes and tumor progression in basal-like breast cancer (BLBC), CRC, lung cancer, and pancreatic cancer." (PMID 35178443, 2022). "BGG is a potent and selective inhibitor of the enzyme aldose reductase (AKR1B1), which is responsible for developing oxidative stress and secondary complications in diabetes." (PMID 36232563, 2022). "In fact, plenty of current studies aimed to find selective inhibitors for AKR1B1 over AKR1B10, and vice versa, in order to exclusively treat complications of diabetes or cancer." (PMID 29532688, 2018). "Studies have shown that βG is a noncytotoxic and selective AKR1B1 inhibitor of aldose reductase, which can protect against oxidative stress and treat secondary complications of diabetes." (PMID 36500465, 2022). "ES-Screen identified previously unreported interactions of the non-steroidal anti-inflammatory drugs (NSAIDs) indomethacin, licofelone, and oxaprozin with human adipocyte fatty acid-binding protein (FABP4) and human aldose reductase (AKR1B1), important targets in metabolic diseases such as diabetes." (PMID 36499162, 2022). "Evidence showed that AKR1B1 overexpression in the lens of transgenic mice led to anterior subcapsular cataracts development, even in the absence of diabetes and hyperglycemia." (PMID 34356319, 2021). "Indeed, the inhibition of aldo-keto reductase family 1 member B1 (AKR1B1, aldose reductase) attenuated inflammation as well as diabetes-induced complications." (PMID 32932589, 2020). "Our data showed that the mRNA level of AKR1B1 was not altered in diabetes." (PMID 32932589, 2020).
diabetes (continued). "Misra P and Chakrabarti R showed that enhanced AMPK activity improved type 2 diabetes metabolic disorder, and our previous studies demonstrated that AKR1B1 overexpression decreased AMPK activation, and increased AcSOD2 and RAGE-induced EMT in the LECs of DM patients with cataracts." (PMID 34356319, 2021). "Several studies have demonstrated that overproduction of AKR1B1 in the LECs would undergo EMT that developed anterior subcapsular cataracts in vivo, even without diabetes and hyperglycemia." (PMID 34356319, 2021).
Hyperglycemia (78 papers, 2007 to 2026). An increased concentration of glucose in the blood. "Sorbinil, a specific AKR1B1 inhibitor, was used to determine the enzyme’s contribution to acute hyperglycemia-induced inflammation." (PMID 40724989, 2025). "In this study, we aim to elucidate the role of enzymes involved in the polyol pathway, particularly AKR1B1, in mediating acute hyperglycemia-induced inflammation in MIO-M1 cells." (PMID 40724989, 2025). "The recruitment of SLUG to the CDH1 promoter was augmented by hyperglycemia, which was attenuated by silencing AKR1B1 and/or SORD." (PMID 38200154, 2024). "More importantly, hyperglycemia-induced phosphorylation of YWHAH was almost completely attenuated by silencing AKR1B1 and/or SORD, strongly suggesting that polyol pathway-derived fructose drives S25 phosphorylation of YWHAH." (PMID 38200154, 2024). "The gene expression levels of AKR1B1, which plays a key role in hyperglycemia-induced diabetic complications, remained unchanged in prostate samples of patients with T2D." (PMID 32932589, 2020). "In our model, we found hyperglycemia increased the polyol shunt by a 1.75-fold change in gene expression for AKR1B1 in neurons at day 42, which is analogous to fold changes from previous long term animal and human studies." (PMID 30470798, 2018). "The most studied enzyme of the AKR1B subfamily is AKR1B1 or aldose reductase, which reduces glucose to sorbitol under hyperglycemia and has been involved in the secondary complications of diabetic disease." (PMID 26222439, 2015). "Aldose reductase (AKR1B1), a key enzyme in the polyol pathway, has been implicated in the hyperglycemia-induced inflammatory response in various cell types, although its role in retinal Müller glial cells under acute glucose stress remains unclear." (PMID 40724989, 2025). "The application of AKR1B1 inhibitors could prevent or delay hyperglycemia-induced pathologies such as nephropathy, neuropathy, and retinopathy." (PMID 32932589, 2020). "Several mechanisms have been proposed to explain how AKR1B1 (aldose reductase 1 beta 1) gene activity leads to hyperglycemia-induced lesions in different tissues, such as at high concentrations in the seminal vesicles, lens, retina, renal medulla and sciatic nerve." (PMID 28805547, 2017). "Also, AKR1B1 catalyzes the reduction of glucose to sorbitol during hyperglycemia." (PMID 39202342, 2024). "This study investigates AKR1B1 activity and its contribution to inflammatory signaling in MIO-M1 human Müller cells exposed to acute hyperglycemia." (PMID 40724989, 2025). "In this study, the effect of acute hyperglycemia on the onset of the inflammatory response in human Müller glial cell line MIO-M1 has been investigated, highlighting the role of aldose reductase (AKR1B1) as a key mediator of this process." (PMID 40724989, 2025). "Moreover, hyperglycemia-induced cytoskeletal rearrangement and CDH1 suppression were attenuated by AKR1B1 and/or SORD knockdown." (PMID 38200154, 2024). "In particular, the pharmacological inhibition of AKR1B1 with Sorbinil not only reduced sorbitol levels but also markedly suppressed NF-κB activation and COX-2 upregulation, directly implicating AKR1B1 in the pro-inflammatory signaling elicited by acute hyperglycemia." (PMID 40724989, 2025). "In non-tumoral diseases, the role of AKR1B1 in EMT has been primarily investigated in the context of chronic tissue remodeling, fibrosis, and organ dysfunction—conditions frequently associated with hyperglycemia, in which the enzyme is overexpressed and hyperactivated." (PMID 41154825, 2025).
diabetic neuropathy (39 papers, 2008 to 2025). A chronic, pathological complication associated with diabetes mellitus, where nerve damages are incurred due to diabetic microvascular injury involving small blood vessels that supply these nerves, resulting in peripheral and/or autonomic nerve dysfunction. "Polymorphisms within the aldose reductase gene, AKR1B1, and its promoter region have been linked to diabetic neuropathies and microvascular complications." (PMID 26074879, 2015). "AKR1B1 is associated with diabetic neuropathy and diabetic autonomic neuropathy." (PMID 28805547, 2017). "AKR1B1 inhibitors, such as epalrestat, are already clinically approved for diabetic neuropathy or lung cancer, underscoring the enzyme’s druggability." (PMID 41173929, 2025). "Encouragingly, epalrestat, an AKR1B1 inhibitor already approved for diabetic neuropathy treatment, effectively mitigated drug resistance in both in vitro and in vivo HCC models." (PMID 40750772, 2025). "For example, AKR1B1 and SORD have been proven to be associated with the occurrence of complications such as diabetic neuropathy." (PMID 33953784, 2021). "This review suggests that polymorphism within ACE, AKR1B1, APOE, MTHFR, NOS3, and VEGF may act as common genetic risk factors for the diabetic neuropathies in T2DM." (PMID 26074879, 2015). "Although the potency for inhibition of AKR1B1 is higher, therapeutic plasma concentrations of ranirestat, which is currently under development for the treatment of diabetic neuropathy are in the micromolar range and might, therefore, be high enough to efficaciously inhibit AKR1C3." (PMID 38175295, 2024). "We assessed changes in gene expression of sorbitol dehydrogenase (SORD) and aldose reductase (AKR1B1) as an indirect measure of polyol pathway flux and, along with protein kinase C (PKD2), as key characteristic markers for diabetic neuropathy." (PMID 30470798, 2018). "The overexpression of AKR1B1 has not only been reported in glomeruli, but also in the peripheral nerves of T2DM patients, where it is thought to contribute to the disease pathology of diabetic neuropathy." (PMID 26074879, 2015).